ERG (ETS transcription factor ERG)
Diseases named in the same sentence as ERG in open-access papers (continued):
Sharing a sentence is not in itself a finding about the gene and the disease.
tumor (continued). "While it is not frequently reported in normal prostate tissue, TMPRSS2:ERG fusions facilitate tumour progression by promoting angiogenesis, inflammation, and epithelial–mesenchymal transition ultimately leading to metastasis, advanced tumour stages, and increased mortality." (PMID 40165885, 2025). "In the absence of CD31 and ERG expression, a positive cytokeratin result may lead to the misdiagnosis of the tumor as epithelial in origin." (PMID 41377863, 2025). "Interestingly, vascular markers CD31, CD34 and ERG highlighted a dense capillar network between tumour nests, without staining of tumour cells, which ruled out an endothelial origin such as angiosarcoma or littoral cell angioma." (PMID 38643139, 2024). "TMPRSS2:ERG is an AR regulatory gene that is restored in CRPC and may promote tumor progression." (PMID 38887275, 2024). "Finally, the evaluation of ERG, TFF3, and SPINK1 could be an attractive approach to determine both tumor heterogeneity and PCa subtypes." (PMID 38256434, 2024). "Interestingly, as with the TCGA model, one main branch of the GSE model (i.e., branch 1) contained a mix of ERG fusion–positive and –negative tumor samples." (PMID 39347576, 2024). "Using ERG expression by IHC as a genetically validated proxy for ERG rearrangement status, we were able to corroborate this finding in the JHU primary tumor cohort (P < 0.0001) with a similar trend in a separate independent primary tumor cohort from the PCBN (P = 0.05)." (PMID 38112617, 2024). "Additionally, ERG hyperactivates inflammatory pathways by interacting with TLR-4, which subsequently activates NF-kb, increasing the transcription of target genes which trigger tumor growth and progression." (PMID 37509339, 2023). "ERG inhibition reduced the expression of VE-cadherin and EGFL7 that may result in decreased proliferation and increased apoptosis due to junction instability, hence, inhibit tumor metastasis." (PMID 37310937, 2023). "Notably, within these early-passage organoids we identified a population fitting our profiling of ERG+ tumor cells, expressing a high level of LE cell markers (KLK3, KLK2, and ACPP) and tumor markers (PCA3, TRPM8, and ERG), which we annotated as putative tumor cells." (PMID 35013146, 2022). "However, our analysis of ERG− tumor cells unexpectedly found that ERG− tumors did not cluster by patient and we observed a shared heterogeneity for ERG- tumor cells with non-malignant luminal cells." (PMID 35013146, 2022). "Cluster 1 was characterized by upregulation of tumor-suppressing genes: HNF1B, CCNDBP1, PATJ, EPB41L3, MARVELD2, PTEN in conjunction with cell-cycle genes – GSPT1, GPR19, EAPP, KIT, CDKL1, and stem cell markers – RBBP5, NANOG, NCSTN, ERG, including quiescent stem cell markers—FOXP1, SMARCA2." (PMID 36348001, 2022). "Interestingly, PTEN was lost in 67% of ERG-positive tumours compared to 31% of ERG-negative tumours (p = 0.006)." (PMID 35159086, 2022). "However, GSEA analysis between ERG+ and ERG− patients for tumor cells, BE, non-malignant LE, and club cells using the C2CP gene-set collection did not detect any common pathway changes shared by these epithelial cell types." (PMID 35013146, 2022). "At ERC, where tumor growth was halted, AR nuclear expression was significantly lower (P < 0.0001), with heterogeneous nuclear localization and scarce cytoplasmic staining; while ERG reactivity was negative (P < 0.0001)." (PMID 34584218, 2021). "However, ERG S96E robustly promoted tumor formation without luminal epithelial differentiation, suggesting that ERG’s ability to promote luminal fates is not the key to ERG’s oncogenic function." (PMID 34314419, 2021). "In agreement with our previous results, we found that ERG-fused cells (VCaP, LuCaP-23.1, −35) were more sensitive to SPOP-i than ERG-negative cells (22Rv1, LNCaP, PC3), while SPOP mutant cells (LuCaP-78, −147) were particularly insensitive in 3D culture models and in xenograft tumor models in vivo." (PMID 33531470, 2021).
tumor (continued). "Importantly, our findings indicate that while ERG redistribution by AKT and ERG-mediated transcriptional repression by PRC2 are necessary for luminal fates, these processes are dispensable for ERG-mediated tumor formation." (PMID 34314419, 2021). "Interestingly, we observed an enrichment for FOXA1 and HOXB13 in Gleason pattern 4 tumours independent of their ERG accessibility." (PMID 34911933, 2021). "Additionally, AA patients with high Gleason grade tumors exhibited primarily ERG negative index tumor type." (PMID 32341752, 2020). "However, the absence of an association between most of these deletions with YAP1 expression in ERG positive and ERG negative tumour subsets argues against a direct role of YAP1 for the control of genome integrity or double strand breakage repair." (PMID 32488048, 2020). "By immunohistochemistry, the tumor cells stained positively for S-100 (focal +), CD34 (strong +++), and Ki-67 (20%), and negatively for smooth muscle actin, pan-cytokeratin (CK), neurofilament (NF), pan-cytokeratin-L, GFAP, CD31, STAT6, ERG, myogenin, and MyoD1." (PMID 32590748, 2020). "This is the first genetic epidemiological study on the association of genetic variants at a genome-wide scale, as opposed to selected SNPs, with TMPRSS2: ERG fusion status both by index tumor or by any tumor foci, considering the multifocal and multiclonal nature of the disease." (PMID 32341752, 2020). "Irrespective of the reason behind, the selective prognostic impact of TFAP2D in ERG negative cancers demonstrates that prognostic markers (or their defining thresholds) depend on other molecular tumor features and the intracellular microenvironment of cancer cells." (PMID 32143573, 2020). "Irrespective of the underlying mechanism, the selective prognostic impact of BAP1 in ERG negative cancers demonstrate, that the applicability (and perhaps thresholds) of prognostic markers may depend on individual molecular tumor features." (PMID 31903168, 2019). "Therefore we are particularly interested in the frequently altered and targetable genes in the ERG-negative tumor type." (PMID 30150711, 2018). "In addition, they detected ERG (by IHC) in only one out of 22 SPOP-mutant human tumor samples, leading them to conclude that mutant SPOP was not regulating ERG178." (PMID 30135717, 2018). "As a result, ERG and FLI1 expression was significantly decreased after a 4-hour conditioned media treatment by all three implanted tumors investigated, indicating that expression of these TFs is at least partially downregulated by soluble factors enriched in the tumor microenvironment." (PMID 30500808, 2018). "Nevertheless, others reported that the metastases may also arise from the tumor without ERG rearrangement." (PMID 28055969, 2017). "Among the 317 tumor foci identified in our cancers, 78 were homogeneously ERG positive (25 %), 176 were homogeneously ERG negative (55 %), and 63 showed a (intrafocal) heterogeneous ERG result (20 %)." (PMID 27530104, 2016). "The complete absence of ERG-positive tumor areas in 6q15-deleted tumor foci further suggest that the functional consequences of 6q15 deletions may prevent the development of TMPRSS2:ERG fusions." (PMID 26684029, 2016). "For the highlighted risk regions, we considered mRNA expression analysis of candidate target genes in fusion-positive and negative tumor tissues, to investigate the mechanistic interplay between the somatic TMPRSS2:ERG phenotype and the germline genotype of associated risk variants." (PMID 27798103, 2016). "In a recent study Grupp and coworkers investigated the impact of mitochondrial content by staining for MTC02 in PCa tissue samples and found a correlation of MTC02 with ERG positive PCa with increased staining intensity in PTEN negative tumor samples within the ERG positive subset." (PMID 26285134, 2015).
tumor (continued). "The inclusion of deletion data from multiple chromosomal loci revealed further, that the relationship of SOX9 and ERG expression largely depended on whether or not a PTEN deletion was present in a tumor." (PMID 26030748, 2015). "Moreover, since progression to high-grade disease was paralleled by a reduction of SOX9 expression in ERG-positive cancers, very strong SOX9 overexpression may even counteract tumor growth." (PMID 26030748, 2015). "Moreover, neither the subtype of EWS–FLI1/ERG in the tumor, nor the detection of fusion transcripts in the peripheral blood (PB) samples, has prognostic value in ES patients." (PMID 25008066, 2014). "In 4,151 ERG negative cancers, strong MTC02 staining was significantly associated with high preoperative PSA-levels (p = 0.0372), advanced pathological tumor stage, high Gleason grade, positive nodal involvement and positive surgical margin status (p < 0.0001 each)." (PMID 24261794, 2013). "In the 24 prostatectomy specimens analyzed by expression arrays, CRISP3 was classified as over-expressed in 62.5% of tumor samples (8 ERG positive and 7 ERG negative) as compared to the non-malignant prostatic tissue, with the remaining showing normal/decreased protein expression." (PMID 21814574, 2011). "Our results support this hypothesis because PTEN loss was only a significant independent prognostic factor for overall survival, when analysed in the ERG/ETV1 gene non-rearranged tumours." (PMID 20104229, 2010). "The mRNA transcripts for the fusion gene TMPRSS2:ERG were detected in two out of the four patients who had a high Gleason score and PSA levels, and not in the two low-risk tumours (patient 3 and 4), whereas PCA-3 transcripts were detected in all of the patients after mild prostate massage." (PMID 19401683, 2009). "However, ERG S96E could promote tumor formation in the absence of activated AKT, indicating that ERG repressive function is somehow inhibiting its ability to promote tumor formation in the absence of a second oncogenic hit." (PMID 34314419, 2021). "Here, loss of JUP, presumably contributing to reduced tumor cell cohesion by disturbing desmosome and adherens junction assembly, might additionally promote the more metastasis‐prone phenotype of CHD1‐deleted cancers within the ERG‐negative subset." (PMID 33533127, 2021). "They found common transcriptional pathways that were upregulated in the tumor, stroma, and CD4 T cell populations of ERG negative patient tumors, including the PD-1 and IFNγ signaling pathway, suggesting that ERG tumor cells may give rise to a distinct immune cell niche in the TME." (PMID 34502458, 2021). "While the overall expression patterns were comparable between ERG-negative and ERG-positive tumors, we found that genomic alterations could affect the same pathway through distinct genes in the same pathway in both groups of tumor types." (PMID 30150711, 2018). "This may be due to the presence of micro foci of tumor in subsequent sections of the tissue extracted for RNA analysis below that originally analyzed by the pathologist and may explain why some ‘benign’ regions unexpectedly showed positive TMPRSS2:ERG expression." (PMID 27144529, 2016). "Thus, these genes might not be primarily related to the tumor status but rather to ERG-induced transcription remodeling." (PMID 22142399, 2011). "If more than 1% of tumor cells exhibit membrane staining, the tumor is considered PD-L1-positive.Meanwhile, the tumor tested negative for CD34, EMA, ERG, S100, HMB45." (PMID 41293148, 2025). "The ERG−/PTEN+ tumour molecular subtype of PCa is described by the absence of ERG rearrangements, such as TMPRSS2:ERG fusions, and the retention of PTEN function, which is important for controlling the PI3K/AKT signalling pathway." (PMID 40165885, 2025). "The tumor cells showed strong diffuse staining for CD31, ERG and FOSB, and negative on CD34 and CAMTA, with a minority of TFE3, CKAE1/AE3+ and EMA." (PMID 40277775, 2025).
tumor (continued). "Immunohistochemical analysis revealed that the tumor cells were positive for CD31, ERG, and Syn, while negative for CKpan." (PMID 40797498, 2025). "Immunohistochemical results showed that the tumor cells expressed Vimentin, SMA, Bcl-2, CD56, CD34, CD31, Ki-67, ERG, RB, INI-1, and SATB2, but were negative for SSTR2 and CK." (PMID 40406261, 2025). "Immunohistochemically, the tumor exhibited diffuse positivity for CD31 and ERG, with no discernible expression of MYC and negativity for TRPS1." (PMID 38902365, 2025). "No immunoreactivity for CK, S100, CD31, ERG, MDM2, CDK4, Melan A, or HMB45 was detected in the tumor cells." (PMID 38388450, 2024). "The liver metastases and PDX tumor histology slides were negative for AR, PSA, PSAP and ERG protein expression; the tumor strongly expressed KRT7 and focally 34βE12." (PMID 38907236, 2024). "Due to the multifocal nature of PCa, tumor foci can be found with and without a TMPRSS2:ERG in individual prostates such that they are present in ~70% of cancerous prostates, making them a more useful biomarker than was originally apparent." (PMID 36765747, 2023). "IHC analysis indicated the tumour cells were positive for CD31, CD34 and ERG and negative for pan-cytokeratin." (PMID 37686662, 2023). "Tumor cells express endothelial cell markers such as CD34, CD31, and ERG, and negative for mesothelial markers." (PMID 38115250, 2023). "All tumours expressed typical endothelial markers CD31, ERG, and CD34 and were negative for pan-cytokeratin." (PMID 37686662, 2023). "ERG protein and ETS RNA was identified exclusively in a nonindex tumor in 31% and 32% of patients, respectively." (PMID 35574900, 2022). "Tumor cells were negative for, CD34, CD31, v-ets erythroblastosis virus E26 oncogene like isoform 2 (ERG), and FLI1." (PMID 35615157, 2022). "This one sample (Patient 6, T4) was ERG‐negative on IHC and displayed a relatively low TMPRSS2:ERG signal on RNA‐seq, likely due to contamination with cells from the nearby ERG‐positive tumor focus T3." (PMID 35220606, 2022). "In the immunohistochemical studies, the tumor was positive for S100 and CD68 but focal positive for neurofilament and negative for ERG and HMB-45." (PMID 34961529, 2021). "Immunohistochemical studies demonstrated that the tumor was positive for S100 and CD68, focal positive for neurofilaments, but negative for ERG and HMB-45." (PMID 34961529, 2021). "The tumor cells typically do not form vessels in PHE but instead are spindle shaped and co-express endothelial markers (CD31 and ERG) and keratin AE1AE3, not all of which are recapitulated in our in vivo model." (PMID 33377124, 2020). "The left-sided tumor was ERG-negative with reduced PTEN in a subset of tumor cells (B1), while the right-sided tumor stained positively for ERG and had homogenous reduction in PTEN expression in both the IDC-P (B2) and invasive (B3) components." (PMID 32054861, 2020). "Consistent with this idea, we find that the expression levels of ETV4, ERG, PIK3CA, and RSPO3 were elevated ~ 80–800-, ~ 25-, ~ 8-, and ~ 10–30-fold compared to the fusion-negative group of the same tumor type, respectively." (PMID 32631391, 2020). "By immunohistochemistry, the tumor was positive for CD31, CD34, ERG, and TFE-3 and negative for PCK, CK8/18, EMA, CK19, Glypican3, hepatocytes, and arginase." (PMID 33121478, 2020). "By immunohistochemistry, tumor cells demonstrated strong nuclear cyclin D1 expression and multifocal smooth muscle actin staining but were negative for MUC4, ERG, CD34, S-100 protein, desmin, STAT6, CD45, MDM2, CDK4, ALK, and ROS1." (PMID 32461620, 2020). "Immunohistochemically, the tumor cells are positive for CD31, ERG, FLI1, and cytokeratin (AE1/AE3), but negative for CD34." (PMID 32316685, 2020).
tumor (continued). "Due to primary tumor unavailability or absence of tumor cells, FISH for AR amplification was feasible in 15/28 (54%) patients, and ERG status by IHC in 19/28 (68%) patients." (PMID 27391263, 2016). "There was no major difference between ERG positive and ERG negative cancers in their relationship with PSA recurrence and tumor phenotype." (PMID 25762627, 2015). "ERG/ETV1 gene rearrangement positive and negative tumours have been reported to have distinct chromosomal aberrations, expression signatures and morphological features, thus suggesting that they represent different PCa classes." (PMID 20104229, 2010). "Neither EWS/FLI-I, EWS/ERG and EWS/FEV fusion genes nor MIC2 expression were found in any tumour, whereas trisomy 8 was found in one case only." (PMID 10574242, 1999). "The comparison of final tumour volumes between treated and untreated conditions revealed that Capmatinib induced a reduction in tumour volume only in mice injected with the PC3M ETV1 and PC3M ERG cell lines and not in control mice." (PMID 39374163, 2025). "Immunohistochemistry of liver metastatic biopsies and PDX tumor showed lack of expression of typical PCa (e.g., AR, PSA, PSAP, ERG) or neuroendocrine markers (synaptophysin), compatible with double-negative CRPC, but was positive for nuclear β-catenin expression, keratin 7 and 34βE12." (PMID 38907236, 2024). "The tumour cells were diffusely positive for smooth muscle actin and GRM1 (in > 95% of the neoplastic cells), focally positive for CD34 and negative for S100 protein, desmin, cytokeratin AE1AE3 and ERG." (PMID 36810795, 2023). "The tumor cells were negative for AE1/3, Cam5.2, CKIT, DOG1, CD99, SOX10, S100, HMB45, MelanA, Syn, CgA, Trypsin, Desmin, SMA, Caldesmon, collagen type 4, Laminin, Inhibin, Calretinin, STAT6, CD34, ERG, WT1, ER, PR, and SALL4." (PMID 36928336, 2023). "Moreover, two cases with ERG rearrangement in IDC-P and lymph node metastases, showed that ERG status was the same in IDC-P and metastasis but discordant in another tumour foci without IDC-P." (PMID 35159086, 2022). "The tumor showed the expression of cytokeratins, such as CK8-18 and AE1/AE3, and typical CD99 expression, whereas immunostaining for thyroglobulin, TTF1, PAX8, calcitonin, CK20, SOX10, ERG, SMA, and NUT was negative." (PMID 36129618, 2022). "ERG S96E can promote tumor formation in the absence of activated AKT signaling, whereas ERG cannot." (PMID 34314419, 2021). "Tumor cells were nonreactive for SF-1, inhibin alpha, desmin, HHF35, HMB45, Melan A, MITF, c-kit, DOG1, cytokeratin AE1/AE3, h-caldesmon, STAT6, CD68, MDM2, CDK4, c17, DHEAST, 3BHSD, CD31, Factor 8, and ERG." (PMID 34797454, 2021). "In contrast, the tumor cells were nonreactive for SF-1, inhibin alpha, desmin, HHF35, HMB45, Melan A, MITF, c-kit, DOG1, cytokeratin AE1/AE3, h-caldesmon, STAT6, CD68, MDM2, CDK4, c17, DHEAST, 3BHSD, CD31, Factor 8, and ERG." (PMID 34797454, 2021). "Due to the natural expression of RIOK2 and ERG in brain endothelial cells (data not shown), NSC139021 may affect the tumor vessels." (PMID 34572430, 2021). "The molecular mechanism by which ERG and AKT synergize to promote tumor formation is not known." (PMID 34314419, 2021). "In addition, the tumor cells were negative for PSA (inset), but positive for androgen receptor, v-ets erythroblastosis virus E26 oncogene homolog (ERG), and alpha-methylacyl-CoA racemase (AMACR)." (PMID 33263827, 2020). "The tumor is negative for EMA, cytokeratin 7, cytokeratin 20, chromogranin A, synaptophysin, S-100 protein, HMB-45, desmin, SMA, EBV, CD117, DOG1, CD23, CD21, clusterin, MDM2, CD34, D240, and ERG." (PMID 31623602, 2019). "In our case, the tumor cells expressed CD31, AE1/AE3, FLi-1, and ERG and were negative for CD34." (PMID 31311568, 2019). "In addition to tumor architecture, differences in clinical and epidemiological characteristics have also been investigated for TMPRSS2:ERG positive and negative PrCa." (PMID 27798103, 2016).